CXCR4 (C-X-C motif chemokine receptor 4)
Description:
Receptor for the C-X-C chemokine CXCL12/SDF-1 that transduces a signal by increasing intracellular calcium ion levels and enhancing MAPK1/MAPK3 activation. Ligand binding causes a conformation change that triggers signaling via guanine nucleotide-binding proteins (G proteins) and modulates the activity of downstream effectors, such as adenylate cyclase. CXCR4 is coupled to G(i) G alpha proteins and mediates inhibition of adenylate cyclase. Involved in the AKT signaling cascade. Plays a role in regulation of cell migration, e.g. during wound healing. Also acts as a receptor for extracellular ubiquitin; leading to enhanced intracellular calcium ions and reduced cellular cAMP levels. Binds bacterial lipopolysaccharide (LPS) et mediates LPS-induced inflammatory response, including TNF secretion by monocytes. Involved in hematopoiesis and in cardiac ventricular septum formation (By similarity). Also plays an essential role in vascularization of the gastrointestinal tract, probably by regulating vascular branching and/or remodeling processes in endothelial cells (By similarity). Involved in cerebellar development; in the CNS, could mediate hippocampal-neuron surviva (By similarity). (Microbial infection) Acts as a coreceptor (CD4 being the primary receptor) for human immunodeficiency virus-1/HIV-1 X4 isolates and as a primary receptor for some HIV-2 isolates. Promotes Env-mediated fusion of the virus.
Synonyms: LESTR; CD184; NPY3R; HM89; NPYY3R; D2S201E; fusin; HSY3RR; NPYR; FB22; LCR1; NPYRL; WHIM; WHIMS; WHIMS1
Tractability: Small molecule: an approved drug acts on it; a structure with a bound ligand is known; a high-quality ligand is known; it has a high-quality binding pocket; it belongs to a druggable protein family. Antibody: a drug acting on it is in phase 2 or 3 trials; UniProt places it where antibodies can reach, with high confidence; its Gene Ontology location is reachable by antibodies, with high confidence; UniProt predicts a signal peptide or a membrane-spanning region. PROTAC: UniProt records ubiquitination sites on it; ubiquitination databases record sites on it; its protein half-life has been measured; a small molecule that binds it is known. Other modalities: a drug acting on it is in phase 2 or 3 trials.
Target class: Peptide receptor (family A GPCR); Membrane receptor; Family A G protein-coupled receptor; CXC chemokine receptor; Chemokine receptor
Chemical probes: TIQ-15, ZALCITABINE
Gene: Protein-coding gene on chromosome 2 (136,114,349 to 136,119,177, reverse strand). Ensembl gene ENSG00000121966.
Subcellular location: Cell membrane; Cell junction; Early endosome; Late endosome; Lysosome
Pathways (Reactome):
Developmental Biology: Developmental Lineage of Multipotent Pancreatic Progenitor Cells; Formation of definitive endoderm; Signaling by ROBO receptors
Signal Transduction: Chemokine receptors bind chemokines; G alpha (i) signalling events
Disease: Binding and entry of HIV virion
Reproduction: Specification of primordial germ cells
Gene Ontology:
Molecular function: actin binding; C-C chemokine binding; C-X-C chemokine receptor activity; C-X-C motif chemokine 12 receptor activity; myosin light chain binding; protein binding; ubiquitin binding; ubiquitin protein ligase binding; C-C chemokine receptor activity; coreceptor activity; G protein-coupled receptor activity; virus receptor activity; chemokine receptor activity; cytokine binding
Biological process: adenylate cyclase-inhibiting G protein-coupled receptor signaling pathway; calcium-mediated signaling; cell chemotaxis; cellular response to cytokine stimulus; CXCL12-activated CXCR4 signaling pathway; G protein-coupled receptor signaling pathway; positive regulation of cell migration; positive regulation of macrophage migration inhibitory factor signaling pathway; positive regulation of vasculature development; regulation of cell adhesion; response to hypoxia; apoptotic process; brain development; dendritic cell chemotaxis; immune response; inflammatory response; myelin maintenance; neurogenesis; positive regulation of cold-induced thermogenesis; positive regulation of cytosolic calcium ion concentration; positive regulation of oligodendrocyte differentiation; response to virus; cell migration; chemotaxis; regulation of cell migration; and 1 more
Cellular component: anchoring junction; cell leading edge; cell surface; cytoplasmic vesicle; early endosome; extracellular exosome; late endosome; lysosome; plasma membrane; protein-containing complex; cytoplasm; external side of plasma membrane; membrane
Genetic constraint (gnomAD): Loss-of-function variants: 6 observed, 23.04 expected, observed/expected ratio (o/e) 0.26, 90% interval 0.14 to 0.51. The upper end of that interval is the gene's LOEUF score, 0.51, which puts it in group 2 of 6, group 1 being the genes least tolerant of losing a copy. Missense variants: 300 observed, 452.15 expected, observed/expected ratio (o/e) 0.66, 90% interval 0.6 to 0.73. Synonymous variants: 155 observed, 181.61 expected, observed/expected ratio (o/e) 0.85, 90% interval 0.75 to 0.98.
Gene-disease validity (ClinGen):
ClinGen rates the evidence that CXCR4 causes each of these diseases.
WHIM syndrome (autosomal dominant): Definitive.
Cancer hallmarks: proliferative signalling (promotes); invasion and metastasis (promotes)
Homologues: Orthologues: chimpanzee CXCR4 (100% identical), macaque CXCR4 (97% identical), dog CXCR4 (96% identical), pig CXCR4 (95% identical), rabbit CXCR4 (94% identical), guinea pig CXCR4 (93% identical), rat Cxcr4 (91% identical), mouse Cxcr4 (91% identical), tropical clawed frog cxcr4 (76% identical), zebrafish cxcr4a (68% identical), zebrafish cxcr4b (63% identical). Paralogues in human: CXCR3 (34% identical), CXCR2 (34% identical), CXCR1 (33% identical), CCR4 (33% identical), CCR9 (31% identical), CXCR5 (30% identical), CXCR6 (30% identical), CX3CR1 (30% identical), ACKR4 (30% identical), CCR6 (30% identical), ACKR2 (29% identical), CCR1 (29% identical), and 11 more.
Diseases named in the same sentence as CXCR4 in open-access papers:
CXCR4 is named in the same sentence as 730 diseases in open-access papers, as found by Europe PMC text mining. Sharing a sentence is not in itself a finding about the gene and the disease. The quoted sentences say what the papers report.
breast carcinoma (976 papers, 2002 to 2026). "In breast cancer, the overexpression of CXCR4 in small EVs was associated with tumor recurrence and distant organ metastases." (PMID 40635521, 2025). "CXCR4 has been established as an independent prognostic biomarker across multiple malignancies, including breast cancer, where its expression is strongly associated with aggressive tumor behavior, metastatic potential and poor clinical outcomes." (PMID 40075611, 2025). "The CXCL12/CXCR4 signaling axis is regulated by the tumor suppressor gene Il-24 and is strongly associated with breast cancer." (PMID 40076586, 2025). "In human breast cancer cell lines, AQP3 peroxiporin activity was found to be implicated in CXCL12/CXCR4-dependent breast cancer cell migration." (PMID 39941100, 2025). "Tumor Metrics: Treatment with rP21 inhibited the expression of CXCR4, a receptor that is overexpressed in breast cancer cells and other tumor cells, and caused the receptor to internalize." (PMID 40297577, 2025). "For instance, in breast cancer, elevated levels of CXCR4 and CXCR7 are linked to increased tumor growth, angiogenesis, and metastasis to the lungs and bone." (PMID 41024311, 2025). "Previous research has demonstrated that the nuclear translocation of CXCR4 is linked with the progression and metastasis of several cancers, including renal cell carcinoma, non-small-cell lung cancer, breast cancer, gastric cancer, and colorectal cancer." (PMID 39195225, 2024). "An active hypoxic factor has been reported in the IL-1 promoter, while hypoxia reduces IL-1 expression in association with an increase in CXCR4 in breast cancer cell lines." (PMID 38956273, 2024). "Another natural flavone luteolin reduced the expression of CXCR4 in human breast cancer cells MDA-MB-231, being associated with the suppression of cellular invasion." (PMID 39465008, 2024). "CCR7 is often up-regulated together with CXCR4 in cancer and is associated with lymph node metastases in breast cancer." (PMID 39001456, 2024). "Our research further supports this association, highlighting that miR-139-5p modulates CXCR4 in HER2 breast cancer drug resistance." (PMID 39682150, 2024). "Both JunB and CXCR4 have been shown to be overexpressed breast cancer, and CXCR4 has been implicated in tumor progression in pancreatic cancer." (PMID 38835488, 2024). "Consistent with our findings, a very recent clinical study showed increased CXCR4 expression in trastuzumab-resistant breast cancer tissues and was associated with a higher risk of recurrence." (PMID 37280713, 2023). "In the present study, based on our previous findings of CXCR4 in trastuzumab resistance, we investigated the therapeutic potential of targeting CXCR4 in trastuzumab-resistant breast cancer models and explored the associated mechanisms." (PMID 37280713, 2023). "In breast cancer, high CXCR4 expression was associated with a favorable survival compared to low CXCR4 expression (left)." (PMID 37749552, 2023). "Here, we report that DPP-4 deficiency promotes breast cancer cell survival via the induction of autophagy by the C-X-C motif chemokine 12 (CXCL12)/C-X-C receptor 4 (CXCR4)/mammalian target of rapamycin (mTOR)/hypoxia inducible factor (HIF)-1α axis." (PMID 37760498, 2023). "The dynamic variation of CXCR4 supports that CXCR4 expression is associated with cell cycle progression in trastuzumab-resistant breast cancer cells." (PMID 37280713, 2023). "High expression of CXCR4 in breast cancer is associated with early distant metastasis and bone metastasis." (PMID 36424557, 2022). "The overexpression of CXCR4 on immunohistochemistry has been shown to be associated with poorer prognosis in breast cancer patients." (PMID 36140541, 2022). "CXCL12/CXCR4-dependent cell migration is a critical process in breast cancer progression; however, its underlying mechanism remains to be elucidated." (PMID 35847914, 2022).
breast carcinoma (continued). "Overexpression of CXCR4 can increase the risk of distant metastasis of breast cancer and reduce the overall survival rate and disease-free survival rate of patients." (PMID 35992864, 2022). "Another study has shown that nuclear CXCR4 expression and lymph node metastases are associated with the prognosis of breast cancer patients." (PMID 33773539, 2021). "In a Korean study, high expression of CXCR4 on membranes, cytoplasm, and breast cancer cell nuclei was associated with younger age, large tumor size, and poor OS." (PMID 33773539, 2021). "CXCR4 is overexpressed in breast cancer cells circulating in the blood, and an association between the plasma level of CXCR4 and circulating tumour cells was confirmed." (PMID 33919589, 2021). "Ca2+-induced CXCR4 expression is found in bone marrow cells in mice and CXCR4-mediated intracellular Ca2+ upregulation is implicated in cell migration in breast cancer and oral squamous cell carcinoma." (PMID 34804954, 2021). "In breast cancer patients, CXCR4 overexpression is associated with lymph node status and poor prognosis." (PMID 34198652, 2021). "Binding of the chemokine CXCL12 to its receptors CXCR4 and CXCR7 is positively associated with the progression of breast cancer; high expression of both CXCR4/CXCR7 has been implicated in the activation of EMT, tumor stemness, and chemoresistance." (PMID 33805447, 2021). "We also examined the mechanisms underlying miR-139-derived inhibition of CXCR4 signaling to decrease the invasion/migration of breast cancer both in vitro and in vivo." (PMID 34070538, 2021). "The clinical data also showed that high expression levels of CXCL12 and its receptors CXCR4 were associated with easy metastasis and poor prognosis of breast cancer." (PMID 35111484, 2021). "Diverse mechanisms underlying the CXCL12/CXCR4-induced therapy resistance have been reported in breast cancer." (PMID 33096815, 2020). "In patients with breast cancer, CXCR4 overexpression is associated with the lymph node status and poor prognosis." (PMID 33096815, 2020). "CXCL12-γ mostly expressed by carcinoma-associated fibroblasts confer to CXCR4-positive breast cancer cells the ability to metastasize into BM through the expression of the receptor activator of NFκB ligand (RANKL)." (PMID 32260318, 2020). "Lung metastasis remains a significant cause of deaths in patients with breast cancer and the CXCR4/CXCL12 pathway is a key player in this process." (PMID 33096815, 2020). "CXCR4 overexpression in tumor tissue is associated with poorer outcomes in several cancers, including breast cancer." (PMID 32836215, 2020). "In breast cancer, organ-specific metastasis is thought to be associated with CXCR4 expression and downstream signalling." (PMID 32836215, 2020). "It has been reported that increased CXCR4 expression in breast cancer tissues is associated with the occurrence of tumor distant metastasis and decreased overall survival in patients." (PMID 32836215, 2020). "High CXCR4 expression was associated with increased bone metastasis and poorer prognosis in breast cancer patients." (PMID 32836215, 2020). "Further, downregulation of CXCR4 in metastatic breast cancer cells was linked to restrained proliferation." (PMID 32346064, 2020). "The chemokine receptor is also frequently overexpressed in invasive breast cancer and the diagnostic performance of CXCR4-directed PET imaging have been successfully assessed in recurrent breast cancer." (PMID 32235331, 2020). "In order to further understand the relationship between CXCR4 expression and bone metastasis of breast cancer, we examined the association between CXCR4 expression and clinicopathological features in breast cancer patients." (PMID 32836215, 2020). "The dominant role of the stromal cell-derived factor 1/C-X-C chemokine receptor type 4 (SDF-1/CXCR4) signaling pathway in promoting breast cancer-associated bone metastasis was described in several studies." (PMID 31963522, 2020).
breast carcinoma (continued). "The CXCR4/CXCL12 pathway in M2 perivascular TAMs has been implicated in breast cancer relapse after chemotherapy in preclinical models." (PMID 33096815, 2020). "Downregulation of the C-X-C motif chemokine receptor 4 (CXCR4) in breast cancer cells metastasized to the lung, has also been associated with sustaining the dormant phenotype." (PMID 31817646, 2019). "To understand the mechanistic aspects of the contribution of NRF1 in susceptibility to the breast carcinogenicity, we focused our efforts on NRF1 motif enriched CXCR4 gene, which is implicated in breast cancer." (PMID 30486409, 2018). "Recent evidence implicates that EGFR, c-erbB2 and its encoding gene HER2/neu, can also regulate CXCR4 expression at the post-transcriptional level in breast cancer cells." (PMID 30564115, 2018). "Overexpression of chemokine receptor type 4 (CXCR4) has been found to be associated with increased cell proliferation, metastasis and also act as an indicator of poor prognosis in patients with breast cancer." (PMID 30564115, 2018). "TGF-β1 and SDF-1 (CXCL-12) and its G-protein-coupled transmembrane receptor, CXCR4, have been shown to be implicated in breast cancer and bone metastasis at many levels." (PMID 30150545, 2018). "The C-X-C motif chemokine receptor 4 (CXCR4) expression has been shown in tumors associated with BM metastases such as breast cancer, prostate cancer, neuroblastoma, and rhabdomyosarcoma." (PMID 30149659, 2018). "In particular, CXCR4 expression in breast cancer was significantly associated with lymph node and distant metastasis and worse overall survival." (PMID 30319622, 2018). "CXCR4 expression has also been linked to over 20 different types of cancer like breast cancer, colon cancer, prostate cancer and melanoma demonstrating that the CXCR4/CXCL12-axis is involved in tumor progression, angiogenesis, metastasis and survival." (PMID 28356064, 2017). "In all the known chemokine receptors, breast cancer cells specifically express active CXCR4, which was associated with metastatic breast cancer." (PMID 28446538, 2017). "Overexpression of IκB in breast cancer cells with constitutive NF-κB activity resulted in reduced expression of CXCR4 and a corresponding loss of SDF-α -mediated migration in vitro." (PMID 28402272, 2017). "Here, we found that the reduced CXCR4 by chitosan nanoparticle-delivered siRNA was associated with increased sensitivity of breast cancer cells to cisplatin." (PMID 28446538, 2017). "Recently, it has been reported that CXCR4 is not only associated with the metastatic spread of breast cancer cells to secondary organs, but it also crucial in the dissemination from the primary tumor site." (PMID 27556298, 2016). "CXCR4 overexpression in tumor tissue was associated with inferior outcome in several cancers including breast cancer." (PMID 26896000, 2016). "One of the major mechanisms underlying the chemotactic attraction of breast cancer cells towards bone has been identified in the CXCR-4/CXCL-12 axis, also critical for other bone-metastasizing tumors, such as prostate cancer." (PMID 27571063, 2016). "Previous reports suggested that engagement of CXCR4 by CXCL12 causes the activation of FAK that contributes to CXCL12-dependant chemotaxis in breast cancer cells." (PMID 26993780, 2016). "Out of all the known chemokine receptors, breast cancer cells specifically express active CXCR4, highly associated with metastatic potential of human breast cancer." (PMID 27556298, 2016). "Silencing ROR1 expression by siRNA reduces the expression of EMT-associated proteins, such as SNAIL-1/2, ZEB1, CXCR4, and vimentin in breast cancer cell line MDA-MB-231." (PMID 27830754, 2016). "In the present study, CXCR4 rs2228014 (C/T) genetic polymorphism and mRNA expression were assessed in 74 female breast cancer patients." (PMID 26576337, 2015).